EGFR (epidermal growth factor receptor)
Diseases named in the same sentence as EGFR in open-access papers (continued):
Sharing a sentence is not in itself a finding about the gene and the disease.
glioma (continued). "We examined whether EGFR feedback activation by BRAFV600E inhibition was evident in vitro, by treating three BRAFV600E glioma cell lines (BRAFV600E homozygous line AM38 and BRAFV600E heterozygous lines DBTRG-05MG and NMC-G1) with 5 μM PLX4720, 1 μM HKI-272 or a combination of both drugs." (PMID 26023796, 2015). "Our studies have shown that the SNX1 protein is up-regulated in gliomas and we could not find differential expression of EGFR in gliomas." (PMID 26370624, 2015). "Additionally, attempts to therapeutically inhibit the EGFR pathway in glioma have not achieved success, but delivery of miR-491 can impact both EGFR and other oncogenic pathways, perhaps achieving more successful results." (PMID 26682264, 2015). "Moreover, pharmacologic inhibition of EGFR combined with inhibition of BRAFV600E to reduce growth of glioma cell lines and orthotopic glioma xenograft by decreasing tumor cell proliferation while increasing apoptosis, with resultant significant extension of animal subject survival." (PMID 26023796, 2015). "Interestingly, EGFR-null glioma cells (Gli36) and parental U87MG (data not shown) are also responsive to Nimotuzumab treatment." (PMID 25886314, 2015). "In contrast to either monothereapy, combined inhibition of BRAFV600E and EGFR, both in vivo and in vitro, resulted in efficient silencing of the MAPK pathway, reflected by reduced tumor growth in and extended survival of animal subjects bearing BRAFV600E glioma xenografts." (PMID 26023796, 2015). "Co-evaluating histological grade and EGFR amplification status showed that grade could prognostically separate EGFR non-amplified lower-grade gliomas (p < 0.0001) but not EGFR amplified lower-grade gliomas (p < 0.811)." (PMID 26369702, 2015). "The combined treatment is effective regardless of the EGFR status in human glioma." (PMID 25886314, 2015). "Our data suggest that this combination may provide an alternative treatment for TMZ-resistant gliomas regardless of the EGFR status." (PMID 25886314, 2015). "It is critical to state that EGFR may not be the only receptor involved in the activation of migration of glioma cells." (PMID 26098895, 2015). "In contrast to a prior report on ELMO1, a regulator of GTPase activation and glioma cell motility, our study suggest that the crosstalk between the CD151-integrin complexes and RTKs converge at ARHGAP26, consistent with its link to the EGFR-mediated cell motility and signaling." (PMID 26377974, 2015). "However, EGFR expression levels have no prognostic value regarding overall survival of glioma patients." (PMID 25594013, 2014). "In contrast, in the EFEMP1-high glioma subset (N = 65), EGFR data analysis had no prognostic value." (PMID 25594013, 2014). "Thus, gliomas with high levels of PDGFRA expression and gliomas with high levels of EGFR amplification and expression may originate from different cellular and genetic origins." (PMID 24489888, 2014). "Importantly, epigenetic/genetic silencing of PHD3 preferentially occurs in gliomas without EGFR amplification." (PMID 25420773, 2014). "Cetuximab and anti-EGFR targeted Affibody were conjugated to two different fluorescent dyes (both emitting in the near-infrared) and injected intravenously into 6 athymic mice which were inoculated orthotopically with green fluorescent protein (GFP) expressing human U251 glioma cells." (PMID 23593208, 2013). "However, the possible implication of EREG in glioma development has not yet been addressed, even though the pathological significance of EGFR has been well established in this pathology." (PMID 24330607, 2013).
glioma (continued). "Aberrant activation of pro-angiogenic signaling pathways that are common in human cancers, e.g., the EGFR/phosphatidylinositol-3-kinase (PI3K)/Akt, vascular endothelial growth factor (VEGF), PDGF, and NF-κB pathways, is important in the development of neovessels in human gliomas." (PMID 24202447, 2013). "There have been several trials of EGFR inhibitors in GBM, mainly using small molecular ATP-competitive tyrosine kinase inhibitors Several phase II trials of EGFR inhibitors such as erlotinib or gefitinib have demonstrated limited effectiveness of these agents for gliomas." (PMID 22918789, 2012). "Thus, in addition to EGFR, SEC61G is an amplification target in a large fraction of the gliomas." (PMID 21170331, 2010). "A survey of 15 human glioma cell lines showed that MAbs against the ectodomain of EGFR could positively identify lines that were negative for EGF binding due to mutations in the EGF binding site or lines with low receptor density." (PMID 20614029, 2010). "Besides EGFR, which is found overexpressed in 40% of gliomas, the genes N-MYC, C-MYC, PDGFR-α, MYB, K-RAS, CDK-4 and MDM2 are the most commonly amplified oncogenes in gliomas." (PMID 18713462, 2008). "The SF763 glioma cell line was chosen for this study because it had the lowest ratio of nuclear to cytoplasmic FABP7 as compared to other cell lines, and induction of FABP7 nuclear translocation by EGFR activation could be easily detected." (PMID 16623952, 2006). "Since both EGFR activation and forced expression of FABP7 promote glioma cell migration, we examined whether inhibiting the expression of FABP7 can suppress glioma cell migration induced by EGF." (PMID 16623952, 2006). "This resulting receptor, known as the de2-7 EGFR, does not bind ligand but displays a low level of constitutive activity and imparts a significant in vivo growth advantage to a number of tumour types including the breast, lung and particularly gliomas." (PMID 15770208, 2005). "However, while in glioma cells expressing high levels of EGFR (GSC83) this receptor was uniformly distributed on cellular surfaces, only a small fraction of their derived EVs contained EGFR, as documented by nano-flow cytometry, ExoView and super-resolution microscopy." (PMID 41953752, 2026). "However, it should be emphasized that none of the EGFR-targeted therapies have shown promising results in clinical trials in patients with glioma, so these positive results of the work on the combination of PDT with EGFR inhibitors should be treated with caution and need to be confirmed clinically." (PMID 39201395, 2024). "In addition, MAPT can alter the characteristics of the glioma mesenchyme by inhibiting EGFR-mediated NF- κB and TAZ signaling pathways, inhibit the transformation of tumor cells into pericytes, normalize tumor blood vessels, and reduce the invasiveness of gliomas." (PMID 35441059, 2022). "However, there are no published studies regarding the interplay between EGFR and AR in gliomas." (PMID 34681618, 2021). "In LN18 glioma cells, isotopologue profiling could not reveal significant differences in 13C-enrichments but also not in the isotopologue compositions of the selected amino acids following 213Bi-anti-EGFR-MAb treatment compared to untreated controls." (PMID 33737524, 2021).
glioma (continued). "Clinical results with rapamycin have been described in patients with high-grade GBM and have demonstrated that treatment with rapamycin or combination with EGFR inhibitors may provide an alternative treatment for TMZ-resistant gliomas, regardless of EGFR status." (PMID 33762015, 2021). "Moreover, Kaplan-Meier analyses of survival showed that high expression levels of p-EGFR but not TRIM24 could serve as a predictor of a worse prognosis for patients with gliomas." (PMID 29129908, 2017). "Notably, most murine models of glioma have not yet been interrogated with human signatures; thus, this analysis also provided a first characterization of the human equivalence, at the molecular level, of the Ink4a/Arf−/−; EGFR* model." (PMID 26923714, 2016). "Accordingly, it had been shown on this paper that the vessel density in xenografts significantly diminished upon NT combination treatment as compared to controls, and this might account in part for why nimotuzumab did not enhance TMZ‐induced cytotoxicity in EGFR‐overexpressing glioma cells in vitro." (PMID 26778701, 2016). "Indeed, beside the regulation of EGFR and β-catenin function, other not known signaling processes could be involved, leading to inhibition of phenotypic hallmarks of glioma." (PMID 23696788, 2013). "However, EGFR-Ras or PI3K mutations alone are not sufficient to transform glial cells, rather multiple mutations that coactivate EGFR-Ras and PI3K-Akt pathways are sufficient to induce glioma." (PMID 19214224, 2009). "However, gliomas typically do not express histiocytic markers and exhibit other molecular characteristics, including IDH mutations, ATRX alterations, 1p/19q co-deletions, EGFR amplification, TERT promoter mutations, H3 mutations, MYB/MYBL1 gene structural mutations, and FGFR1 mutations, etc." (PMID 40231251, 2025). "We also found that PU-H71 downregulated EGFR and its downstream signaling pathway proteins, including AKT, S6, and MAPK, in glioma cells with and without MGMT methylation." (PMID 39682123, 2024). "On the other hand, in the 75 Grade 4 glioma cases, 14 cases (18.6%) had wildtype IDH1 and 74 cases (98.6%) had no EGFR-amp." (PMID 38893240, 2024). "In glioma cells, but not NHAs, potent PU-H71-mediated HSP90 inhibition resulted in the downregulation of pro-survival client proteins such as EGFR, MAPK, AKT, and S6." (PMID 39682123, 2024). "EGFR amplification was also observed to be limited to IDH wildtype (26%) and TERT mutant (27%) gliomas, occurring irrespective of MGMT promoter methylation status and being mutually exclusive with 1p/19q co-deletion (LOH)." (PMID 38893240, 2024). "Among the 26 grade 3 glioma samples, 4 cases (15.3%) had wildtype IDH1, and 26 cases (100%) had no EGFR-amp." (PMID 38893240, 2024). "Expression of RTKs, including epidermal growth factor receptor (EGFR), fibroblast growth factor receptor (FGFR), platelet-derived growth factor receptor α (PDGFR α) as well as Gαi3 was not significantly changed in P1 glioma cells with YEM1L shRNA/KO." (PMID 37051674, 2023). "In response to NLGN3, multiple RTKs (VEGFR2, EGFR and FGFR1) as well as Gαi1 and Gαi3 were enriched in the endosomal fraction in P1 glioma cells, but not in Gαi1/3-silenced cells." (PMID 34373757, 2021). "Whereas the LG DI tumor showed common glioma changes, such as EGFR upregulation, and ERK/MAPK and CD44/c-SRC pathway activation, the latter involved in glioma cell invasion, the HG LM component lacked these changes." (PMID 33853673, 2021). "For example, PKCα links the EGFR and mTORC1 pathways, independent of the AKT pathway, which participates in glioma viability." (PMID 33916593, 2021). "MiR-450a-5p exhibited a negative correlation with the EGFR via targeting the 3′UTR of EGFR, and regulated the EGFR-induced PI3K/AKT/mTOR signaling pathway in glioma cells." (PMID 32820249, 2020).
glioma (continued). "All these results indicate that miR-450a-5p exhibits a negative correlation with the EGFR, and regulates the EGFR-induced PI3K/AKT/mTOR signaling pathway in glioma cells." (PMID 32820249, 2020). "Although the status of EGFR was not analyzed, the effect of BMP4 on glioma cells was mediated by its downstream targets, p21CIP1 and ID1 (DNA-binding protein inhibitor 1)." (PMID 32788653, 2020). "Unlike the strategy of targeted therapy in EGFR mutant NSCLC, neither TKIs nor immune checkpoint inhibitors were widely used in glioma at present." (PMID 31801484, 2019). "A biomodulatory approach involving EGFR small-molecule TKIs, although not successful as stand-alone treatments for glioma due to the rapid development of resistance and other issues, could for a short temporal window weaken glioma cells enough to improve the efficacy of PDT if well-timed." (PMID 31847378, 2019). "Copy number of EGFR and HER2 was not different between low-grade gliomas (LGGs) and high-grade gliomas (GBMs); however, copy number of HER3 and HER4 was significantly increased in LGGs as compared to GBMs." (PMID 29190914, 2017). "No statistical survival advantage was observed with EGFR nor with PDGFRA transcripts despite the distinct differences at mRNA and protein levels between IDH-wildtype and IDH-mutant gliomas." (PMID 27852048, 2017). "Knock-down of ROCK1 in glioma cells did not significantly influence EZH2, EGFR, XIAP and BMI1 expression, which indicates miR-340, regulates these oncogenes through distinct mechanisms bypassing ROCK1." (PMID 25831237, 2015). "We have previously demonstrated that glioma migration induced by CXCL12 is specifically abolished by inhibitor of KCa3.1, with mechanisms independent of those activated by EGFR." (PMID 24023874, 2013). "The overexpression of wild type and vIII mutant forms of EGFR lacking the 3′-UTR rescued cells from the inhibitory effect of miR-219-5p on MAPK and PI3K pathways and also on glioma cell migration." (PMID 23690991, 2013). "As for glioma, no studies have reported that IFN-γ stimulation could directly modulate EGFR expression or EGFR activity." (PMID 37759950, 2023). "Notably, no changes in the amount of phosphorylation of EGFR or NF-kB were observed in TMZ-treated SVZ-EGFRvIII tumors compared to controls, reinforcing the lack of response of these gliomas to the drug." (PMID 36325374, 2022). "Of all gliomas without LOH 1p/19q, 11% showed EGFR amplification." (PMID 35453544, 2022). "Of all gliomas with LOH 1p/19q, none showed an EGFR amplification." (PMID 35453544, 2022). "Importantly, our fully annotated cohort displays a wide variety of genetic features not recapitulated in other models (e.g., EGFR and PDGFRA amplification), thus reflecting the wide interpatient heterogeneity of high-grade gliomas." (PMID 33009951, 2020). "In vitro, PDT was performed on a subset of the available human cell lines, with EGFR driven U87 and U87vIII, cells representing PDGFR subtypes, and U373vIII, the patient-derived glioma stem cell line GSC-30 and the non-EGFR expressing GS2 cell line provided controls." (PMID 31847378, 2019). "The median age at diagnosis of adult H3 K27M-mutant gliomas was 32 years, with a midline location (spinal cord, thalamus, brainstem, or cerebellum); at molecular level, these tumors had a low rate of MGMT promoter methylation and lacked EGFR amplification." (PMID 30279357, 2018). "Unlike glioma, EGFRvIII expression in HNSCC did not correlate with EGFR amplification." (PMID 25658924, 2015).
glioma (continued). "Since other target genes, such as MMP16 and EGFR, were also involved in the modulation induced by miR-146b-5p, the prognostic significance of TRAF6 was not as important as that of miR-146b-5p in gliomas." (PMID 26320176, 2015). "Our present work reveals that the silencing of PHD3, which occurs during glioma progression, primarily affects tumor growth by different mechanisms that do not depend on HIF, but centre around the control of EGFR activity, resulting in a net stimulation of cell growth coupled to reduced apoptosis." (PMID 25420773, 2014). "To investigate possible molecular mechanisms underlying this association, we compared the expression and subcellular localization of FABP7 in non-tumor brain tissues with different types of glioma, and examined the expression of FABP7 and epidermal growth factor receptor (EGFR) in GBM tumors." (PMID 16623952, 2006). "Consequently, grade 2 and 3 glioma patients with EGFR amplification (copy number fold change > 1.2, n = 103) had higher level of TAM-SPP1 (p < 0.0001) as well as higher score of TAM-SPP1 marker genes compared to patients without EGFR amplification." (PMID 38515213, 2024). "Additionally, the TMB of EGFR fusion patients was further analyzed, which indicated that the TMB of EGFR fusion was higher than that of non-EGFR fusion but with no statistical significance, no matter in pan cancer or in the lung, gastric cancer, and glioma." (PMID 39054543, 2024). "An Immunohistochemistry study demonstrated that in high-grade (WHO grade III–IV) glioma samples, there was a clustering of antigen expression into “distinct neighborhoods.”53 For example, in areas of pseudopalisading necrosis, IL-13Rα2 and HER2 were expressed, but EGFR was not." (PMID 38486856, 2024). "The MUC4/MMP9/EGFR combined low expression significantly predicted better survival in glioma patients in comparison with the ‘double high’ group and the difference was again more significant than the previous analysis that combined MMP9 and MUC4 only (without EGFR) (p = 0.004, Log-rank)." (PMID 36400876, 2022). "YTH n6-methyladenosine RNA binding protein 2 (YTHDF2) is downstream of epidermal growth factor receptor/src proto-oncogene, non-receptor tyrosine kinase/extracellular signal-regulated kinase (EGFR/SRC/ERK) and plays an important role in the proliferation and invasion of glioma cells." (PMID 35004688, 2021). "While recent approaches with small-molecule tyrosine inhibitors (TKIs) targeting epidermal growth factor receptor (EGFR) have been successful in other cancer indications such as lung and ovarian cancer, they did not provide a significant increase in survival time for glioma patients." (PMID 31847378, 2019). "However, follow-up clinical studies could not confirm the widespread EGFR amplified CD34+ endothelial cells in gliomas, and hence transdifferentiation, while important, may be a rare event in the evolution of gliomas." (PMID 28740831, 2017). "In glioma, EGFRvIII is present almost exclusively in tumors with EGFR gene amplification, however a recent study in HNSCC indicated that EGFRvIII expression may not be correlated with EGFR gene amplification." (PMID 25658924, 2015). "In these glioma cells expressing either wt or EGFRvIII receptor, elevated cell death observed in the Nimotuzumab group correlated with reduced levels of activated AKT in both cell types, providing further support that Nimotuzumab acts regardless of EGFR status." (PMID 25886314, 2015). "Besides, though MMP-9, EGFR, GST-π, and TOPO II all play crucial roles in the progression, invasion, migration and dissemination of gliomas, their expression levels do not differed among divergent recurrence groups, indicating that the recurrence pattern may not be determined by these molecules." (PMID 33585189, 2020).